GPR55 (G protein-coupled receptor 55)
Description:
G protein-coupled receptor that binds to several ligands including 2-arachidonoyl lysophosphatidylinositol or lysophosphatidylglucoside with high affinity, leading to rapid and transient activation of numerous intracellular signaling pathways. Induces the Ca(2+) release from intracellular stores via ERK, the heterotrimeric G protein GNA13 and RHOA leading to morphological changes including cell rounding and stress fiber formation. In macrophages, acts downstream of lysophosphatidylglucoside to inhibit the translocation of the phospholipid-transporting ABCA1 to plasma membrane and subsequent cholesterol efflux leading to lipid accumulation and foam cell formation.
Synonyms: LPIR1
Tractability: Small molecule: a structure with a bound ligand is known; a high-quality ligand is known; it belongs to a druggable protein family. Antibody: UniProt places it where antibodies can reach, with high confidence; its Gene Ontology location is reachable by antibodies, with high confidence; UniProt predicts a signal peptide or a membrane-spanning region. PROTAC: a small molecule that binds it is known.
Target class: Membrane receptor; Small molecule receptor (family A GPCR); Family A G protein-coupled receptor; Lysophosphatidylinositol receptor; Lipid-like ligand receptor (family A GPCR)
Chemical probes: CID2440433, ML-191, ML-193, ML185, ML186, ML192
Gene: Protein-coding gene on chromosome 2 (230,907,318 to 230,961,066, reverse strand). Ensembl gene ENSG00000135898.
Subcellular location: Cell membrane
Pathways (Reactome):
Signal Transduction: Class A/1 (Rhodopsin-like receptors); G alpha (i) signalling events
Gene Ontology:
Molecular function: cannabinoid receptor activity; G protein-coupled receptor activity; protein binding
Biological process: bone resorption; G protein-coupled receptor signaling pathway; negative regulation of osteoclast differentiation; phospholipase C-activating G protein-coupled receptor signaling pathway; positive regulation of ERK1 and ERK2 cascade; positive regulation of Rho protein signal transduction; cannabinoid signaling pathway
Cellular component: plasma membrane; membrane
Genetic constraint (gnomAD): Loss-of-function variants: 11 observed, 17.8 expected, observed/expected ratio (o/e) 0.62, 90% interval 0.39 to 1.02. The upper end of that interval is the gene's LOEUF score, 1.02, which puts it in group 4 of 6, group 1 being the genes least tolerant of losing a copy. Missense variants: 376 observed, 427.21 expected, observed/expected ratio (o/e) 0.88, 90% interval 0.81 to 0.96. Synonymous variants: 183 observed, 176.23 expected, observed/expected ratio (o/e) 1.04, 90% interval 0.92 to 1.17.
Homologues: Orthologues: chimpanzee GPR55 (99% identical), macaque GPR55 (97% identical), dog GPR55 (85% identical), rabbit GPR55 (80% identical), pig GPR55 (77% identical), mouse Gpr55 (77% identical), guinea pig GPR55 (74% identical), rat Gpr55 (74% identical), tropical clawed frog gpr55 (42% identical), zebrafish gpr55a (29% identical). Paralogues in human: GPR35 (32% identical), LPAR6 (28% identical), LPAR4 (27% identical), P2RY10 (24% identical), F2RL3 (23% identical), GPR18 (23% identical), F2R (22% identical), F2RL1 (22% identical), GPR17 (22% identical), P2RY8 (22% identical), CYSLTR1 (21% identical), GPR20 (20% identical), and 4 more.
Diseases named in the same sentence as GPR55 in open-access papers:
GPR55 is named in the same sentence as 149 diseases in open-access papers, as found by Europe PMC text mining. Sharing a sentence is not in itself a finding about the gene and the disease. The quoted sentences say what the papers report.
Obesity (26 papers, 2015 to 2026). Accumulation of substantial excess body fat. "With respect to metabolic syndrome, emerging data suggest that GPR55 and LPIs are associated with obesity and adipogenesis." (PMID 34502436, 2021). "A current study has shown that GPR55 deficiency in mice was associated with increased obesity, reduced physical activity and energy expenditure." (PMID 31121839, 2019). "LPI and oleoylethanolamide promote insulin release from isolated mouse islets, and in humans modulation of the LPI/GPR55 system has been positively linked with increased obesity by poorly understood mechanisms." (PMID 30148676, 2019). "The present study investigated whether CID16020046, a selective antagonist of GPR55, could modulate obesity-induced airway inflammation caused by a high-fat diet (HFD) in C57BL/6 mice." (PMID 39000464, 2024). "Similarly, the lysophosphatidylinositol-GPR55 system has been positively associated with human obesity." (PMID 34884889, 2021). "Collectively, our observations indicate that therapeutic modulation of peripheral GPR55 activity may provide a means for countering obesity-linked metabolic dysfunction and insulin resistance and improving the metabolic status of such tissues." (PMID 30148676, 2019). "Another study indicated that the LPI/GPR55 system could be positively associated with obesity in humans." (PMID 31121839, 2019). "It remains unclear whether increased expression of GPR55 in visceral fat is a cause or consequence of obesity or if the stimulatory effects of LPI on fat genes can be repressed by selective GPR55 receptor antagonists." (PMID 30148676, 2019). "The LPI/GPR55 axis has been shown to be positively associated with obesity in human." (PMID 26784247, 2016). "The G protein-coupled receptor GPR55 has been proposed as a new cannabinoid receptor associated with bone remodelling, nervous system excitability, vascular homeostasis as well as in several pathophysiological conditions including obesity and cancer." (PMID 25970609, 2015). "In light of GPR55’s role in promoting inflammation in various experimental models, such as colitis, non-alcoholic steatohepatitis, atherosclerosis, and asthma associated with obesity, this research explores the potential of inhibiting GPR55 for treating autoimmune diseases affecting the joints." (PMID 40429822, 2025). "Some studies have indicated that the LPI/GPR55 system is a novel target in obesity, and it has recently been suggested to be involved in T2DM development." (PMID 41601646, 2026). "The findings suggest the potential application of the GPR55 antagonist CID16020046 in obesity-induced airway inflammation." (PMID 39000464, 2024). "The correlation of LPI and GPR55 showed that increased concentration of LPI augmented the GPR55 level in people with obesity, which is in turn in a positive relationship with weight, BMI, and percent of fat mass." (PMID 36296989, 2022). "The cannabinoid receptor type 1 (CB1R) inverse agonist rimonabant, which was in the past used for the treatment of obesity, is also a GPR55 agonist, although under some conditions it can behave as an antagonist." (PMID 32904155, 2020). "In accordance, central and peripheral administration of GPR55 agonist O-1602 stimulated food intake in the short-term and increased obesity in the long-term." (PMID 31121839, 2019). "It is reported that GPR55 expression in adipose tissue is positively correlated with obesity in humans, particularly in women." (PMID 27941994, 2016). "Notably, LPI/GPR55 positively correlates with human obesity, and GPR55 agonists stimulate food intake, exacerbating obesity." (PMID 38397045, 2024). "Our data suggests that GPR18 has a role in skeletal muscle metabolism, just like the traditional cannabinoid receptors CB1 and CB2, and the other putative cannabinoid receptor GPR55, all of which have previously been shown to be expressed in skeletal muscle and all of which have a role in obesity." (PMID 32824681, 2020).
Obesity (continued). "Research focusing on GPR55 in obesity shows that GPR55 expression is significantly greater in the adipose tissue of obese humans when compared with lean individuals, these data are consistent with our observations of GPR55 expression in the DIO rat kidney compared to chow-fed controls." (PMID 30707678, 2019). "Therefore GPR55 expression appears to vary depending on species, dietary intake and tissue type, and may also be a beneficial therapeutic target for obesity-related comorbidities such as type 2 diabetes mellitus." (PMID 30707678, 2019). "These opposing effects between healthy and obese pre-diabetic mice could be related to changes in the expression of GPR55 during obesity development, in parallel to the well-known changes that take place in the endocannabinoid system during this disease’s development." (PMID 28638091, 2017). "Thus, while it was proposed that increased GPR55 activity might promote obesity in humans, genetic deletion of the receptor in male mice does not result in leanness or in attenuated body weight loss by rimonabant treatment (present data)." (PMID 27941994, 2016). "In mouse models lacking GPR55 in the liver, there is a diminished insulin transmission in skeletal muscle and adipose tissue, resulting in induced obesity." (PMID 38397045, 2024). "O-1602 and O-1918 are atypical cannabinoid ligands for GPR55 and GPR18, which may be novel pharmaceuticals for the treatment of obesity by targeting energy homeostasis regulation in skeletal muscle." (PMID 32824681, 2020). "However, the therapeutic efficacy of GPR55 antagonists against obesity-induced airway inflammation has not been studied." (PMID 39000464, 2024). "Whether or not GPR55 has a direct role in the development of obesity and diabetes has remained an open question." (PMID 27941994, 2016). "In contrast to GPR55 and 119, GPR18 is engaged in obesity-mediated inflammation, but there is a lack of evidence of its direct effects on hepatocytes." (PMID 33498537, 2021).
Anxiety (20 papers, 2013 to 2025). Intense feelings of nervousness, tension, or panic often arise in response to interpersonal stresses. "In 5xFAD mice, a genetic AD animal model, hippocampal GPR55 expression was increased and was associated with memory impairment and anxiety-like behavior." (PMID 38931342, 2024). "In C57BL/6J mice, chronic social defeat stress (CSDS) induced depression- and anxiety-like behavior that was associated with a reduced GPR55 protein synthesis with maintained GPR55-mRNA expression in hippocampal areas of susceptible mice." (PMID 38796643, 2024). "Chronic social defeat stress (CSDS) induced depression- and anxiety-like behavior in mice was associated with a reduced hippocampal GPR55 expression." (PMID 38931342, 2024). "In previous works, GPR55 activation has been associated with an amelioration of anxiety-like symptoms in mice, similarly, a GPR55 modulation of anxiety-like behaviors was also observed in rats." (PMID 37372090, 2023). "Several studies have suggested that the activation of GPR55 in the hippocampus may be implicated in the modulation of anxiety-like behaviors." (PMID 40998031, 2025). "Of particular relevance in adolescent use, some involve, though not limited to, GPR55 in epilepsies resulting from heterozygous mutation to the Scn1a gene, 5-HT1a receptors in anxiety, depression, and protection against acute stressors, and PPARs and TRPV receptors on digestive and gut health." (PMID 34512286, 2021). "Confirming the previously discussed anxiolytic effects of O-1602, GPR55 synthesis was negatively correlated with anxiety-like behavior and novel object exploration but positively correlated with locomotion." (PMID 38796643, 2024). "In Wistar rats, the GPR55 agonist O-1602 promoted anxiolytic-like behavior, while the antagonist ML-193 elicited anxiety-like behavior." (PMID 38931342, 2024). "GPR55 knock-out mice expressed anxiety and motor activity levels comparable to those of wild-type mice while showing impaired thermal sensitivity and motor coordination." (PMID 38931342, 2024). "Electroacupuncture or GPR55 activation by O-1602 both ameliorated CSDS-induced depression- and anxiety-like behavior, and the GPR55 antagonist CID16020046 reversed the positive effects of electroacupuncture." (PMID 38931342, 2024). "Another significant finding of this study is the higher GPR55 expression in the basolateral amygdala of the AppNL-G-F mice compared with the WT mice group, suggesting a potential involvement in anxiety and fear." (PMID 37372090, 2023). "Here, we aimed to explore further the implication of additional CBD proposed targets, such as CB1r, CB2r and GPR55, given the critical role these receptors play in emotional reactivity, anxiety and mood disorders." (PMID 35455470, 2022). "Next, a panel of behavioral tests was used to examine the effect of GPR55 activation on anxiety-like symptoms." (PMID 28800762, 2017). "To investigate the influence and role of GPR55 in anxiety/depression-like behaviors, we used the acute restraint model." (PMID 28800762, 2017). "Overall, these results further confirm that GPR55 is involved in anxiolytic response and that pharmacological enhancement of GPR55 function can reverse anxiety/depression-like behaviors after acute stress." (PMID 28800762, 2017). "In a previous study in which the GPR55 agonist O-1602 was used, it was shown that activation of GPR55 relieved anxiety-like behaviors in normal rats." (PMID 28800762, 2017). "Downregulation of GPR55 expression in the MO cortex of CRS mice raises the possibility that GPR55 influences the development of anxiety, possibly acting as a compensatory response after stress." (PMID 28800762, 2017). "Taken together, the present findings show that O-1602 ameliorated anxiety-like symptoms and reversed stress-induced suppression of glutamate receptor expression through GPR55 activation." (PMID 28800762, 2017).
Anxiety (continued). "The present study was conducted to explore the possible mechanisms by which GPR55 regulates anxiety and to evaluate the effectiveness of O-1602 in the treatment of anxiety-like symptoms." (PMID 28800762, 2017). "Overall, these results suggest that GPR55 play an important role in anxiety/depression-like behaviors and activation of GPR55 can reverse anxiety/depression-like behaviors after acute stress." (PMID 28800762, 2017). "In the present study, the effects of GPR55 agonist and antagonist on stress-induced anxiety-like behaviors were evaluated." (PMID 28800762, 2017). "To explore the possible role of GPR55 in regulating anxiety levels in mice, we performed both elevated plus maze and open field tests." (PMID 23565223, 2013). "Integrating the results of these studies, GPR55 KO mice showed essentially normal baseline anxiety levels and slightly reduced reactivity to a novel environment, but habituated normally." (PMID 23565223, 2013). "Another study focusing on anxiety-like behavior of male Wistar rats using the elevated plus-maze test, showed anxiolytic effects of intracerebroventricular O-1602 injections, while the commercial GPR55 antagonist ML 193 increased anxiety-like behavior." (PMID 38796643, 2024). "GPR55 is widely expressed in brain and it has been proposed as a potential target for the treatment of anxiety and depression since its activation alleviates anxiety-like symptoms in mice subjected to acute stress." (PMID 34062987, 2021). "Future studies may reveal whether GPR55 shows anxiolytic effect in other models of stress-induced anxiety, such as predator scent stress or chronic unpredictable stress." (PMID 28800762, 2017). "Our study results clarified the role of GPR55 in stress-induced mood disorders, and suggested that GPR55 may serve as a potential therapeutic target for the treatment of clinical anxiety or depression." (PMID 28800762, 2017). "Interestingly, CID16020046 prevented LH-21-induced behavioural changes, thus strongly suggesting a key role of GPR55 in mediating the LH-21-driven changes in anxiety." (PMID 28638091, 2017). "Taken together, these results suggest that GPR55 plays an important role in anxiety and O-1602 may have therapeutic potential in treating anxiety-like symptoms." (PMID 28800762, 2017). "We next examined whether intra-vHipp GPR55 activation may influence anxiety levels, using the light/dark box anxiety test protocol." (PMID 28861501, 2017). "Although altered ERK signaling in the cortex of mice with anxiety/depression has been documented, it is unclear whether GPR55 plays any modulatory role." (PMID 28800762, 2017). "Interestingly, GPR55 knockout mice were reported to have similar anxiety-like behaviors as wild-type mice." (PMID 28800762, 2017). "Therefore, our work confirms the specific role of GPR55 in the modulation of anxiety." (PMID 28800762, 2017). "However, the exact role of GPR55 in the modulation of anxiety is unknown." (PMID 28800762, 2017). "While the motor function deficit seen on the rotarod test could be caused by novelty-induced anxiety when mice are introduced to the apparatus, GPR55 KO mice showed no signs of anxiety in either the elevated plus maze or open field assays, making this explanation unlikely." (PMID 23565223, 2013). "GPR55, which is activated by both eCB and non-eCB ligands, plays a role in anxiety regulation, suggesting a broader involvement of the eCBome in anxiety modulation." (PMID 40605060, 2025). "Activation of GPR55 using O-1602 inhibited the activation of the inflammasome, normalizing the increased expression of IL-1β (IL-6 and TNF) and the decreased expression of IL-4 and IL-10, respectively reducing the depression- and anxiety-like behavior." (PMID 38796643, 2024). "The G protein-coupled receptor 55 (GPR55) is a novel cannabinoid receptor, whose exact role in anxiety remains unknown." (PMID 28800762, 2017).
Anxiety (continued). "Deleting GPR55 function did not affect behavioral assays assessing muscle strength, gross motor skills, sensory-motor integration, motor learning, anxiety or depressive behaviors." (PMID 23565223, 2013). "In contrast, GPR55 and their WT littermates appear indistinguishable from one another in measures of anxiety/depression, sensory-motor gating and fear conditioning behaviors." (PMID 23565223, 2013). "CBD can also exert an agonistic action on the 5-HT1a receptor that may explain its antiemetic and anxiolytic-like properties, on the GPR55 enhancing neuronal excitability, and on the TRPV1, highly localized in the hippocampus, reducing anxiety and aversive memories." (PMID 33803374, 2021).